MCL1 (MCL1 apoptosis regulator, BCL2 family member)
Diseases named in the same sentence as MCL1 in open-access papers (continued):
Sharing a sentence is not in itself a finding about the gene and the disease.
tumor (continued). "Mcl-1, a member of the antiapoptotic Bcl-2 protein family, is highly expressed in various tumor types and is associated with poor prognoses and poor clinical outcomes owing to tumor resistance to anticancer drugs." (PMID 34391437, 2021). "Moreover, it has been shown that up-regulation of miRNA-101 inhibited tumor progression, at least in part, by targeting Mcl-1, and associated with poorer prognosis." (PMID 32212793, 2020). "Therefore, these rare populations of tumour cells (that had tolerated Cre activation while harbouring Mcl1fl/fl alleles) had emerged with MCL-1 expression intact." (PMID 29339815, 2018). "We observed increased levels of MCL1 in tumour tissue deficient for Huwe1." (PMID 28003334, 2017). "Since, activated STAT3 protects tumor cells from apoptosis and promote cell growth by regulating multiple genes associated with cell proliferation and anti-apoptotic proteins such as surviving cyclin D1,c-Myc, Fas, Mcl-1, Bcl-xL, and Bcl-2." (PMID 29254150, 2017). "Importantly, this increased DNA damage phenotype sensitises Huwe1‐deficient tumours to treatment with DNA‐damaging agents and depletion of the anti‐apoptotic protein MCL1." (PMID 28003334, 2017). "Furthermore, PIAS1 knockdown experiments revealed an increased expression of tumor suppressor p21 and declined expression of anti-apoptotic protein Mcl1, which caused diminished cell proliferation and tumor growth in vitro and in vivo." (PMID 25474038, 2014). "However, patients with strong Mcl-1 expression were significantly associated with a higher proportion of tumor localization at the stomach (P = 0.020) and strong OPN expression (P = 0.007)." (PMID 24947165, 2014). "As this variant lacks important regulatory parts of the PEST sequence we hypothesized that tumor cells expressing this Mcl1 variant may gain survival advantages and escape certain death stimuli." (PMID 23872733, 2013). "Loss or destabilization of Mcl1 disrupts epithelial homeostasis, amplifies inflammatory signaling, and accelerates tumor initiation, whereas its adaptive upregulation in established malignancy promotes tumor cell survival, metabolic fitness, and therapeutic resistance." (PMID 42194042, 2026). "Emerging evidence exhibits that CDC4 has been confirmed as a tumour suppressor due to the wide involvements in degradation of diverse proteins associated with oncogenic developments, including cyclin E, c-Myc, c-Myb, c-Jun, Notch, MCL1, MED13/13L, PGC-1α, C/EBPα, TGIF1 and KLF5." (PMID 40260685, 2025). "Constitutive ablation of the anti-apoptotic gene Mcl1 in the intestinal tract of Vil1Cre/Mcl1fl/fl mice has been shown to cause chronic apoptosis and inflammation in crypts, with associated hyperproliferation and dedifferentiation leading to the development of malignant tumours." (PMID 40013494, 2025). "Besides, mutated MCL-1 guards tumour cells from therapy-incited decease and drug resistance." (PMID 36267139, 2022). "Regarding the prognostic role of Mcl-1 expression, we performed a Kaplan–Meier study where we observed that high Mcl-1 levels were related to a lower disease free survival and a higher risk of patient recurrence, indicating that Mcl-1 could be a good prognostic marker of tumor aggressiveness." (PMID 30563080, 2018). "Since MCL-1 functions as a potent inhibitor of apoptosis and its aberrant results in impaired apoptosis, our observations was in agreement with a previous report that impaired apoptosis would cause abnormal cell growth and lead to certain malignant phenotypes, such as tumor invasion and metastasis." (PMID 28659182, 2017). "Furthermore, Msln stimulated PI3/Akt and MAPK/ERK signaling and inhibits pro-apoptotic factors such as Bad and Bax and causes the tumor cells to survive for longer periods, and at the same time promotes the expression of anti-apoptotic gene such as Bcl-2 and Mcl-1." (PMID 27626699, 2016).
tumor (continued). "Therefore, our studies suggest that the simultaneous elevation of the pro-survival factor Mcl-1 provides a protection mechanism allowing Fbw7-deficient cells to evade apoptosis, thus providing a novel molecular mechanism for the tumor suppression function of Fbw7." (PMID 21608150, 2011). "miR-29a, although also a tumor-suppressive miRNA regulating apoptosis, extracellular-matrix turnover, and the anti-apoptotic factor MCL1, showed the opposite acute response." (PMID 41596268, 2026). "MCL-1 inhibition downregulates MYC and activates the STAT1-interferon inflammatory pathway, promoting cytotoxic T-cell infiltration with reduced tumor-associated myeloid cells both in vitro and in vivo." (PMID 41680300, 2026). "MCL1 levels varied between patient tumour tissues and MCL1 intensity correlated with CDK9 intensity." (PMID 41505030, 2026). "Previous studies have reported that AZD4573 induces cell death through down-regulation of anti-apoptotic molecules, such as MCL1, and shows a significant anti-tumor effect in acute myeloid leukemia in vitro and in vivo." (PMID 40713627, 2025). "Together, our results indicate that STM2457 enhances anti-tumor effects of venetoclax by decreasing the expression of both MCL1 and MYC." (PMID 40169588, 2025). "In in vivo models, MCL-1 inhibition led to complete clearance of senescent tumor cells and metastases, whereas BCL-2 inhibition with Navitoclax resulted in only partial effects." (PMID 41298369, 2025). "The combined treatment strongly impaired the translation of oncogenic proteins, such as MYC and MCL-1, and increased their proteasome-dependent degradation, thus favouring tumour cell death." (PMID 39533070, 2025). "The prognosis of patients harboring Mcl1-positive tumors was significantly more dismal than those with an Mcl1-negative tumor." (PMID 40765835, 2025). "MCL-1 regulates tumor-cell survival and mitochondrial membrane permeabilization in a variety of tumor cells." (PMID 41049425, 2025). "The down-regulation of miR-375-3p levels in SCLC will lead to increased expression of target genes (such as MYC and MCL1), promoting the proliferation and survival of tumor cells." (PMID 40332288, 2025). "The established role of MCL1 in antagonizing apoptosis is undoubtedly crucial for the tumor- promoting functions of MCL1." (PMID 41326406, 2025). "Maritoclax, a specific MCL1 inhibitor, reversed irinotecan/SN38 resistance in FBW7‐deficient CRC cells and xenograft models, synergizing with irinotecan to suppress tumor growth." (PMID 41312772, 2025). "Taken together, here we describe tumor-promoting roles for MCL1 in regulating mTORC1 signaling and subsequently in bioenergetics, besides its role in antagonizing apoptosis, identifying MCL1 as a hinge of cell bioenergetics and survival." (PMID 41326406, 2025). "It has potential anti-tumor effects in vivo by influencing the expression of the anti-apoptotic protein Mcl-1, reducing the potential of the mitochondrial membrane, triggering autophagy, and other mechanisms [1071, 1072]." (PMID 40490812, 2025). "Taken together, MCL1 inhibition demonstrated anti-tumor activity in several PCa models, including those resistant to treatments that target the AR, which remains a major unmet clinical need in PCa medicine." (PMID 41438049, 2025). "Multivariate analysis revealed that Mcl1 expression was an independent prognostic factor, as were lymph node metastases and tumor size." (PMID 40765835, 2025). "BH3 mimetics, such as venetoclax and MCL1 inhibitors, can reprogram the tumor immune microenvironment to enhance ICI responses." (PMID 41155156, 2025). "Compared to other Bcl2 family members, we found relatively high average mRNA levels of Bcl‐xl (BCL2L1), Bax, and Mcl‐1 in the three tumor organoid lines, while another key member Bcl‐2 exhibited comparatively lower expression." (PMID 40405831, 2025).
tumor (continued). "Our findings demonstrated that 9c effectively inhibited tumor malignancy through cell cycle arrest and apoptosis induction with the transcriptional downregulation of anti-apoptotic genes including survivin, Mcl-1, Bcl-2, and XIAP." (PMID 40076615, 2025). "The limited sample size also prevented a robust evaluation of significant associations between MCL-1 expression and documented prognostic factors, including age, liver enzyme levels (ALT and AST), subtypes, and tumor location." (PMID 40380182, 2025). "Here, we demonstrated that high MCL-1 expression was correlated with metastasis and tumor size, which are prognostic markers of canine HCC." (PMID 40380182, 2025). "Combined treatment induces apoptosis via downregulation of Bcl-xL and Mcl-1, abolishes mitochondrial respiration, and creates bioenergetic conflict that collapses tumor energetics." (PMID 41155556, 2025). "In patient-derived cell lines, we did not observe a clear trend in BCL2L1 (BCL-xL gene) nor HRK mRNAs, probably due to higher inter-tumor variability compared to the MCL-1:NOXA adaptation." (PMID 40113795, 2025). "In the HCC group, enhanced MCL-1 expression showed a positive correlation with tumor size > 5 cm (P = 0.046) and tumor metastasis (P = 0.034), which were documented as a poor prognosis." (PMID 40380182, 2025). "In the HCC samples, high MCL-1 immunostaining was substantially correlated with metastatic status (P = 0.034) and tumor size (P = 0.046)." (PMID 40380182, 2025). "It was found that in tumour cells, knockdown of PTBP1 caused MCL1 mRNA to accumulate in the cytoplasm in addition to increasing MCL1 mRNA levels, upregulating the cytoplasmic/nuclear ratio, but not decreasing the amount of mRNA in the nucleus." (PMID 40579921, 2025). "FBXW7, as a critical tumor suppressor, targets various substrates for proteasome-mediated degradation of oncoproteins, including cyclin E, c-Myc, Mcl-1, mTOR, Jun, and Notch." (PMID 39747664, 2025). "In an experimental mouse lung-metastasis model of intravenously injected human cell lines, the expression of growth factors by tumor-associated stromal cells within the lung pre-metastatic niche drive ERK phosphorylation and MCL1 expression." (PMID 40374715, 2025). "Downstream targets BCL-6 and MCL-1 showed increased expression, correlating with disease aggressiveness (advanced stage and high tumor grade, P < 0.001)." (PMID 40612845, 2025). "Studies conducted in living organisms have demonstrated that reducing the amount of MCL1 level can significantly slow tumor growth." (PMID 39931465, 2025). "As with other tumor cells, treatment of Neuro-2a cells with opaganib decreased the expression of both c-Myc and Mcl-1 (48% and 70%, respectively) and completely eliminated pERK." (PMID 38730731, 2024). "We propose that MARCHF5 induces the degradation of the MCL1 antagonist NOXA thus reinforcing the pro-survival role of MCL1 in these tumor cells." (PMID 39386614, 2024). "Mechanistically, we find that MARCHF5 induces the turnover of NOXA protein thereby reinforcing the pro-survival role of MCL1 in these tumor cells." (PMID 39386614, 2024). "High MCL-1 expression correlated with tumor malignancy (p < 0.001), large tumor size (> 3 cm) (p = 0.005), high Ki-67 expression (p = 0.046), and metastasis (p = 0.027)." (PMID 39012900, 2024). "We discovered that injection of c-MYC/MCL1/Cre into Rictorfl/flTsc2fl/fl mice induced a lethal tumor burden within 1.7–4.0 weeks after injection, whereas in control mice, a fatal tumor burden occurred 4.1–8.7 weeks after injection." (PMID 39325536, 2024). "The intensity of expression of MCL1 in both cell lines was overall congruous with Fra-1 expression—that is, low in the primary tumor, with elevated, heterogeneous expression in metastases." (PMID 37676378, 2024). "As with other tumor cells, opaganib reduced c-Myc and Mcl-1 protein levels in Neuro-2a cells, and also reduced the expression of the N-Myc protein." (PMID 38730731, 2024).
tumor (continued). "We found that exposure to FGF2, FGF18, HBEGF, IGF1, PDGF-BB, and TGFα significantly (p < 0.0001) increased MCL1 expression in tumor cells (by at least 1.2-fold and up to 2-fold) and treatment with the MEKi reduced this response." (PMID 37676378, 2024). "Targeting MCL-1 protein is a successful strategy to induce apoptosis and overcome tumor resistance to chemotherapy and targeted therapy." (PMID 39689117, 2024). "While it is well established that MCL1 is important in anti-apoptotic activities, the data presented here suggest the need for additional evaluation of its role in modulating the tumor immune microenvironment." (PMID 38523186, 2024). "The percentage of high MCL-1 expression increased significantly with tumor malignancy, with rates of 8%, 53%, and 75% in normal, benign, and malignant mammary gland tissues, respectively." (PMID 39012900, 2024). "CircMTO1 was found to mediate the progression of human granulosa-like tumor cells through the miR-320b/MCL1 axis, promoted by increased transcription of SNAI2." (PMID 38255975, 2024). "MCL1 inhibitor S63845 was the only drug that was more effective in several of the modified lines compared to the sensitive tumor line." (PMID 38667326, 2024). "PRT1419 is a potent and selective MCL1 inhibitor with anti-tumor efficacy in diverse preclinical models of solid and hematologic malignancies, which is currently being evaluated in a Phase 1 clinical trial (NCT05107856)." (PMID 38371625, 2024). "In these malignancies, pharmacological inhibition of MCL1 has demonstrated potential to inhibit tumor growth and restore sensitivity to standard of care agents (S.o.C)." (PMID 38371625, 2024). "MDM2 amplification prominently destructs FBW7 tumor suppressor and stabilize MCL-1 anti-apoptotic protein to evade apoptotic cell death." (PMID 39543744, 2024). "Paucatalinone A also decreased the expression of Mcl-1, Bcl-2 and elevated cleaved caspase-3 levels in tumor cells, which were involved in mitochondria-mediated apoptosis." (PMID 38590635, 2024). "We further examined the direct effects of inhibiting MCL1 specifically in tumor cells, in vitro and in vivo, using both B16.F10 and YUMM 1.7 cells." (PMID 38459020, 2024). "In the context of tumor therapeutics, particular attention is given to the anti-apoptotic Bcl-2 proteins including Bcl-2 and Mcl-1 that are frequently overexpressed in tumors." (PMID 39372954, 2024). "Niche cells produce growth factors that increase ERK phosphorylation and MCL1 expression in tumor cells." (PMID 37676378, 2024). "Accumulated evidence suggested that the efficacy of ABT-737, ABT-263, and Venetoclax was reduced because tumor cells upregulated the compensatory Mcl-1." (PMID 39372954, 2024). "Using mouse models, we determined the effects of the MCL1 inhibitor S64315 on tumor growth, tumor-infiltrating MDSC frequency, CD8+ T cell function, and the efficacy of anti-PD-1 therapy." (PMID 38459020, 2024). "In FaDu tumor cells, we found that levels of anti-apoptotic proteins Bcl-xL and Mcl-1 decreased, while levels of pro-apoptotic proteins Bax and cleaved caspase-3 increased." (PMID 39123466, 2024). "Like BCL-2, the related myeloid cell leukemia (MCL)-1 protein exerts anti-apoptotic effects to protect tumor cells." (PMID 39272790, 2024). "Upon activation, phosphorylated STAT3 translocates into the nucleus and promotes the expression of target genes such as cyclin D1, survivin, Bcl-xL, and MCL-1, which are involved in tumor cell proliferation, angiogenesis, and immune evasion." (PMID 39123466, 2024).
tumor (continued). "We found that niche cells produce growth factors that increase ERK activity and MCL1 expression in tumor cells, and that these growth factors are transcribed more highly in metastasis-bearing lungs." (PMID 37676378, 2024). "The drug significantly reduced growth of MDA-MB-453 MIND xenograft tumours, as determined using bioluminescent imaging and reduced protein expression of MCL-1 in tumours." (PMID 38001268, 2024). "This study presents KS18, a new and effective Mcl-1 inhibitor, exhibiting considerable anti-tumor efficacy in both in vitro and in vivo models of MM." (PMID 39411073, 2024). "Myeloid cell leukemia-1 (MCL-1), a member of the Bcl-2 gene family, is highly expressed in many tumor tissues and participates in regulating multidrug resistance." (PMID 38468814, 2024). "As in the scRNA-seq analysis of the BCL2 family, tumor-infiltrating MDSCs expressed higher levels of MCL1 than the other major anti-apoptotic proteins BCL2 and BCL-XL." (PMID 38459020, 2024). "It is worth noting that UMI‐77 was originally known as an apoptosis activator by selectively inhibiting MCL‐1 in tumor cells." (PMID 38482753, 2024). "MiR-15a-5p, as a suppressor of tumour formation, promotes apoptosis and inhibits tumour growth by targeting specific oncogenes, such as Bcl-2, CcnD1, Mcl1, and Wnt3A." (PMID 38698968, 2024). "We show that this mitochondrial E3 ubiquitin ligase targets the MCL1 antagonist NOXA for degradation and consequently reinforces MCL1 function in protecting tumor cells from apoptosis." (PMID 39386614, 2024). "The tumor cell develops this resistance in part by overexpressing anti-apoptotic proteins MCL-1 and BCL-XL58." (PMID 38548768, 2024). "The PRKCSH-IGF1R axis in tumor cells impairs caspase-8 activation, increases Mcl-1 expression, and inhibits caspase-9, leading to an imbalance between cell death and survival." (PMID 38200153, 2024). "The levels of c‐Myc and Mcl‐1 were strongly reduced in tumor tissues from the combined group, together with a noticeable increase in caspase‐3 cleavage." (PMID 39254172, 2024). "Most of the reported Mcl-1 inhibitors have poor anti-tumor activity due to poor physical and chemical properties, low mitochondrial membrane penetration, and high serum protein binding rate." (PMID 39372954, 2024). "Obatoclax is an early pan-BCL-2 inhibitor that can antagonize BCL-2, BCL-xl, BCL-w, and MCL-1 and promote the activation of Bax/Bak and subsequent caspase-3 activation, ultimately leading to the apoptosis of tumor cells." (PMID 39060763, 2024). "Altogether, these results suggest MCL1 inhibition, either directly or indirectly through CDK9 inhibition, has potent anti-tumor activity in PBRM1-deficient ccRCC." (PMID 38371625, 2024). "In this study, we demonstrated that Paucatalinone A induced tumor cell mitochondria disruption mediated by anti-apoptotic proteins (Bcl-2, Mcl-1), pro-apoptotic family member ERK1/2, or calcium and ROS-triggered mitochondrial permeability transition." (PMID 38590635, 2024). "This high binding affinity to MCL-1 translated to cellular efficacy, where cell death at subnanomolar concentrations was observed in tumor cell lines derived from MM (AMO-1, H929) and AML (MV4-11)." (PMID 37880389, 2023). "MCL-1 is an important pharmacological target since it is an emergent resistance factor in tumor cells treated with BH3 mimetics, such as ABT-199 (venetoclax), ABT-263 (navitoclax) and ABT-737." (PMID 37684238, 2023). "MCL1 methylation has been associated with poor overall survival in KIRC patients, while IGF1R and CCND1 methylation have been linked to tumor aggressiveness." (PMID 37744271, 2023). "Nevertheless, evidence suggests a therapeutic window for MCL-1 inhibitors can be achieved, where tumour cells are killed but healthy cells are spared." (PMID 36755070, 2023). "We observed high nuclear and cytoplasmic expression of MCL1 in all tumour tissues examined, with more homogeneously high expression of MCL1 in the metastasis." (PMID 37723317, 2023).